KRAS (KRas proto-oncogene, GTPase)
Diseases named in the same sentence as KRAS in open-access papers (continued):
Sharing a sentence is not in itself a finding about the gene and the disease.
tumor (continued). "In KRAS-driven PDAC mouse models, CAFs were shown to overexpress CXCR2 ligands promoting migration, invasion, and angiogenesis, and in fact, blocking the CXCLs-CXCR2 axis resulted in tumor cell apoptosis, decreased vessel density, and modulation of the immune infiltrate." (PMID 31847096, 2019). "It is known that tumors with KRAS mutations at codons 12, 13, 61, or 146 do not respond to treatment with anti- EGFR antibodies or TKIs and therefore mutational analyses on all RAS genes are carried out on tumor biopsies before a therapeutic regimen is chosen." (PMID 31612113, 2019). "A higher frequency of mutant KRAS may be related to increased tumour density, although this was not evaluated in the current study." (PMID 30774772, 2019). "Additionally, the GC patient with wild-type KRAS-amplified tumor had poorer survival compared to those without KRAS amplification." (PMID 30965636, 2019). "Therefore, in the context of KRAS mutations, ARID1A does not appear to function tumor suppressive, but rather facilitates the expression of genes particularly dependent on the MEK/ERK pathway." (PMID 31217031, 2019). "Moreover, TEPs mRNA profiles could distinguish mutant KRAS, EGFR, or PIK3CA tumours, which is a crucial application in oncology." (PMID 31248203, 2019). "Moreover, studies using patient samples, cultured in 3D conditions and in the presence of tumor microenvironment (TME) components, may provide more realistic insights on the factors that cooperate with mutant KRAS." (PMID 31847096, 2019). "It successfully identifies tumor-specific spliced and non-spliced epitope candidates, which can be further validated as targets for anti-cancer immunotherapies, as illustrated by the HLA-A*02:01+ KRAS G12V+ spliced epitope candidate here described." (PMID 31803176, 2019). "In our study all 30 cases with BRAF V600E mutation showed unequivocal positive cytoplasmic staining in 85–100% tumor cells; all 30 cases with wild-type KRAS and BRAF were negative; 6.7% (4/60) cases with KRAS mutation showed heterogeneous, cytoplasmic/nuclear staining at stain intensity." (PMID 29127628, 2019). "In proof‐of‐concept preclinical studies involving genetically engineered and xenograft (human cell line and patient‐derived) KRAS mutant LAC models, the genetic and therapeutic targeting of ADAM17, the latter with a new class of specific ADAM17 prodomain inhibitor, markedly suppressed tumor growth." (PMID 30833304, 2019). "In relation to this, it was also shown that in non-small-cell lung cancer, oncogenic KRAS alters asparagine biosynthesis via the oxidative stress-responsive NRF2 and ATF4 transcription factors, to suppress apoptosis in response to glutamine deprivation and to sustain tumor growth." (PMID 31852884, 2019). "In addition, the associations of LUNAR1 with sex, age, tumour location, MSI, KRAS mutation, BRAF mutation, and PIK3CA mutation were not statistically significant." (PMID 31882986, 2019). "However, neither WT or mutant KRAS showed tumor formation in vivo in 15 days, whereas fibroblasts expressing KRAS G12V formed progressive tumors." (PMID 31681616, 2019). "Treatment with 5-FU-based regimens improved prognosis in patients with the combination of MSS tumours, KRAS mutation and CIMP negative (log rank P = 0.003) as well as in patients with MSS tumours plus BRAF and KRAS wild-type and CIMP negative (log-rank P<0.001)." (PMID 30188916, 2018). "Demographics and baseline characteristics were well balanced between patients with mutant tumours (i.e., KRAS/NRAS mutation in tissue and/or KRAS mutation in blood, n = 92) and those with wild-type tumours (i.e., neither KRAS/NRAS mutation in tissue nor KRAS mutation in blood, n = 30)." (PMID 29362371, 2018). "Interestingly, of the four patients with a wild type primary tumor, two showed no mutations, while, among the others, one showed EGFR p.E746_A750del, and the other the KRAS p.G12V mutation." (PMID 30110953, 2018).
tumor (continued). "C-PIK3CA-esiRNA application did not decrease KRAS protein levels on DLD1 tumor sections." (PMID 30001368, 2018). "Interestingly, the rate of KRAS mutation in plasma did not appear much different between patients with KRAS wild-type and those with KRAS mutant tumours." (PMID 29362371, 2018). "This pathway involves the accumulation of inhibitory mutations at the level of tumor-suppressor genes and activating mutations at the level of oncogenes and are associated with colorectal tumors exhibiting MSS, non-CIMP, CIN, absent KRAS and BRAF mutations, and APC mutations." (PMID 29652830, 2018). "Furthermore, the brain metastasis #1 (BM1) showed a private (i.e., not present in the primary tumor or in the other synchronous brain metastases) amplification on chromosome 12p12.1, encompassing the KRAS gene." (PMID 29755676, 2018). "The remaining case presented KRAS G12D in the primary tumour but none in ovarian metastasis." (PMID 29662660, 2018). "Although they use sensitive assay with a detection limit of at least 0.5% V600E tumor cells, the copy number of mutant versus wild-type alleles in their cells, cross-reactivity with non-target BRAF mutations, and KRAS mutation status were not clearly described." (PMID 29879227, 2018). "Our results also suggested that 64Cu-PCTA-cetuximab could be used to treat peritoneal dissemination of tumor cells expressing EGFR, with or without a KRAS mutation." (PMID 29989003, 2018). "Indeed, IKKα is required for the MPE-competence of KRAS-mutant tumor cells by activating non-canonical NF-κB signaling." (PMID 29445180, 2018). "Thanks to next generation sequencing (NGS) and circulating tumor DNA (ctDNA) studies, the authors also showed the mechanisms of resistance to anti-EGFR drugs, such as the presence of EGF-R negative tumor clones, KRAS mutation/amplifications, PTEN deletion, and NRAS/HER2/MYC amplifications." (PMID 30205505, 2018). "Our findings add a new twist to this mystery as we reveal that RAS at the GC, which includes H- and N- isoforms but not KRAS, actually antagonize tumor formation through induction of PTPRκ that downregulates ERK activity, the engine at the heart of RAS transformation." (PMID 30185827, 2018). "Given that KRAS and MYC are currently therapeutically undruggable genetic alterations found in many tumor types, a greater understanding of the interaction and cooperativity between these oncogenic changes and GATAD2B may open up the exploration of new therapeutic approaches." (PMID 30013058, 2018). "Since the mechanisms by which metabolic alterations interact with signaling downstream from mutated BRAF and KRAS have not been completely elucidated, the aim of our study was to investigate the impact of BRAFV600E and KRASG12V on tumor cell metabolism and signaling." (PMID 29907857, 2018). "We identified seven oncogenes (NRAS, EGFR, RXRA, HRAS, KRAS, AKT1, ERBB2; q<0.10) and seven putative tumor suppressor genes (ARID1A, TXNIP, CTNNB1, PIK3RI, CDKN2A, KLF5, STAG2; q<0.10) significantly regulated between tumor and control, which were formerly reported to be altered in BC." (PMID 30419021, 2018). "This patient did not have certain sexual history and had KRAS-mutant tumor." (PMID 30458812, 2018). "However, the concomitant activation of Wnt/β-catenin signaling and expression of a constitutively active KRAS mutant, such as KRASG12D, led to a marked increase of tumor formation, in terms of both tumor size and number of tumor lesions, compared with KRASG12D alone." (PMID 30060526, 2018). "Importantly, we observed PI3K dependence in KRAS deficient clones derived from 6/7 (86%) parental cell lines, suggesting that PI3K represents a convergent target regardless of tumor cell line or species of origin." (PMID 29061961, 2017). "No KRAS and BRAF mutations were identified in the same tumor." (PMID 28422723, 2017). "First, matched tumor tissue KRAS analysis was not available for this cohort." (PMID 29228650, 2017).
tumor (continued). "As has been previously demonstrated, key biomarkers (such as mutant KRAS) may be present in the primary tumor, but not the metastatic clones, or vice versa, and prior treatment can impact their presence in the recurrent tumor." (PMID 28469732, 2017). "Moreover, the in vivo anti-tumor effect (tumor growth delay and survival improvement) of the 6F6 mAb in mice xenografted with CLDN-positive CRC cells seems to be independent of KRAS mutational status." (PMID 28659146, 2017). "KRAS is a key downstream effector of EGFR, and permanent activation of KRAS as a result of mutation causes cells to grow without exogenous stimulation and drives tumor initiation." (PMID 28077799, 2017). "However, in the cetuximab arm of the OPUS and CRYSTAL trials, the ORR and PFS of patients with KRAS mutant tumors were much worse (ORR, 26.0 and 31.3% respectively; PFS, 5.5 and 7.4 months, respectively) than patients with no tumor mutations in our study." (PMID 28068936, 2017). "Notably, known CRC drivers (APC, FBXW7, and KRAS) did not segregate according to tumor ploidy status." (PMID 28073006, 2017). "It will be highly interesting to understand whether for LUAD and PAAD, within each tumor type, there are differences in the distribution of KRAS substitutions between smokers and non-smokers." (PMID 26902163, 2016). "In our series, we did not assess KRAS status on the primary tumor." (PMID 26715198, 2016). "With respect to tumor specific mutations, we failed to reveal significant differences for PFS (HR, 1.30; 95% CI, 0.66-2.56) and OS (HR, 1.05; 95% CI, 0.49-2.25) when NSCLC patients were grouped according to KRAS genotype detected in cfDNA." (PMID 27323821, 2016). "The tumor did not harbor either EGFR or, KRAS mutations or ALK rearrangement." (PMID 27150058, 2016). "Of significance is the fact that KRAS and BRAF mutations are preferentially found as alternative molecular alterations and thus are not frequently observed in the same tumor suggesting that KRAS and BRAF have distinct roles in the development and progression of CRC." (PMID 27602501, 2016). "Furthermore, there are no results demonstrating reproducibility of KRAS testing in the primary biopsy as well as in the resected specimen within the same tumor tissue (referred to as intratumoral heterogeneity)." (PMID 27064574, 2016). "Currently, however ROS1 testing is often part of a second phase of testing in a patient whose tumour is negative for more common, routinely tested alterations such as EGFR and KRAS mutation and ALK gene rearrangement and who is a lifelong never or long-time ex-smoker." (PMID 27535289, 2016). "However, tumor-free survival did not significantly differ among the kRas/Akt3, kRas/Akt3/Cdc20, and kRas/Akt3/c-Myc mice." (PMID 26993778, 2016).
tumor (continued). "In order to determine the functional role of these kinases in KRAS-induced transformation, we generated KRAS-positive A549 and H358 cells with stable and inducible shRNA-mediated knockdown of AURKA or AURKB and evaluated transformation in vitro and tumor growth in vivo." (PMID 26842935, 2016). "This tumor was found to be KRAS and BRAF wild type, and EGFR was not overexpressed." (PMID 26909603, 2016). "In this latter tumor, we have found that ACKR2 expression is downregulated in more aggressive tumors by the activation of the KRAS/BRAF/ERK pathway, thus unleashing chemokine-mediated macrophage recruitment and their acquisition of an M2-like phenotype that sustains angiogenesis and tumor growth." (PMID 28123388, 2016). "Therefore, treatment with anti-EGFR mAbs previously only required confirmation of KRAS wild-type status; however, in 2013, the European Medicines Agency (EMA) revised the therapeutic indication, restricting it to patients with RAS wild-type mCRC tumours only." (PMID 27784278, 2016). "Likewise, genetic and pharmacological validation of the hit TBK1 found no reproducible requirement for TBK1 in the growth of KRAS-mutant tumor cell lines in vitro." (PMID 27096871, 2016). "However, our study clearly demonstrated that the primary tumor site (left- or right-sided) is a useful biomarker for predicting the prognosis after cetuximab treatment in patients with advanced KRAS wild-type (exon 2 nonmutant) CRC." (PMID 27221731, 2016). "In addition to KIT and KRAS, there was an over-representation of mutations in cell division cycle 27 (CDC27) (11.9%; 5 mutations, 5 tumours) and PRKRIR (4 mutations, 2 tumours), neither of which have been previously reported as TGCT drivers." (PMID 25609015, 2015). "Somatic mutations occurring before and after chromosome aneuploidy events had distinct VAF values, which allowed inference of the timing of two candidate driver mutations in this tumor, the nonsynonymous mutation of FGFR4 V550L and the nonsynonymous mutation of KRAS codon G12." (PMID 25768946, 2015). "Finally, 4 patients with PIK3CA mutations in cfDNA, but not FFPE tumor samples, had simultaneous KRAS mutations in cfDNA and FFPE tumor samples." (PMID 25980577, 2015). "With regard to molecular tumor characteristics, MT1-MMP expression did neither correlate with the presence of an activating KRAS or BRAF mutation nor correlate with MMR protein expression at the leading edge of the examined tumors in our sample set (P = 0.812, 1.0, and 0.471, resp)." (PMID 26106602, 2015). "Focal KRAS amplification was detected in one tumor, but we could not determine whether this event was present prior to crizotinib treatment or was acquired following treatment due to the absence of a pre-treatment sample." (PMID 25691052, 2015). "Importantly, tumor KRAS status was known in nearly all (98.7%) patients prior to prescribing panitumumab (with or without oxaliplatin-containing therapy), with tumor wild-type KRAS confirmed in 97.7% of patients." (PMID 26491871, 2015). "However, the initiation of KRas(G12D)-driven lung tumors in these mice was accelerated by ATG5 deletion, emphasizing that autophagy may prevent oncogenesis, but promote tumor growth." (PMID 25617802, 2015). "Thus, the insensitivity of KRAS mutant tumors to ixazomib is not explained by lower tumor exposure or less target inhibition." (PMID 26709701, 2015). "The similar ixazomib concentrations and 20S proteasome inhibition in SW48 WT and G13D isogenic tumors suggests that KRAS pathway activation does not alter tumor exposure or target inhibition by ixazomib, but rather affects cellular response to proteasome inhibitor-induced stress." (PMID 26709701, 2015).
tumor (continued). "A further important observation from mouse models and human CRC is that mutations activating KRAS and BRAF do not necessarily result in tumor formation in the intestinal epithelium, due to the existence of fail-safe mechanisms suppressing tumor growth after MAPK activation." (PMID 26299805, 2015). "Interestingly, in the US in 2010, of those patients with mutant KRAS tumor status, only 86% were not treated with EGFR-targeted therapies, suggesting that 14% received anti-EGFR-treatment." (PMID 26491871, 2015). "However, preclinical trials in mice indicate that while suppression of KRAS signaling prevents tumor initiation and progression, it fails to eradicate established tumors." (PMID 26158412, 2015). "In the multivariate analysis, age, gender, clinical T and classification, tumor grade, location, and size, interval between radiation and operation, KRAS oncogene status, and EFGR expression significantly did not affect the tumor response after preoperative CRT." (PMID 26252300, 2015). "However, let-7 restoration does not trigger apoptosis in KRAS mutant tumor cells, limiting its anticancer potency against pre-established tumors." (PMID 25946136, 2015). "KRAS is a target of miR-27a in tumors, particularly in ESCC, and downregulation of the KRAS oncogene may provide a novel treatment strategy for cancer patients by attenuating tumor growth." (PMID 25436011, 2015). "Nevertheless, from 40–60% of patients with wild-type KRAS tumours do not respond to such therapy." (PMID 25932044, 2015). "However, to the best of our knowledge, a possible association between MT1-MMP protein expression and molecular (KRAS/BRAF mutation status) and morphologic tumor characteristics (invasion pattern/budding) has so far not been investigated." (PMID 26106602, 2015). "With reference to this design, we hypothesized that primary tumor location of the left colon might have a favorable prognostic effect in patients with KRAS wild-type tumors, but not in patients with KRAS mutant tumors." (PMID 24816724, 2014). "Oncogenic K-ras might not necessarily be expressed across an entire tumor, but rather cellular subpopulations may exist which display the wild-type KRAS gene." (PMID 24368337, 2014). "Carnosine was also shown to inhibit KRAS-mediated HCT116 proliferation, to inhibit metastasis of SK-Hep-1 invasive hepatocarcinoma cells by inhibiting expression and activity of matrix metalloproteinase 9, and to eliminate tumor cells from a mixture of normal fibroblasts and HeLa cells." (PMID 24886661, 2014). "However, the same dose of P7170 was not very effective in mice bearing erlotinib-insensitive H1975 [EGFR T790M, L858R; KRAS wild type; PIK3CA wild type] xenografts, but treatment with a15 mg/kg dose resulted in a significant tumor growth inhibition (92% TGI, p < 0.001)." (PMID 25466244, 2014). "We speculate that linking INK4-ARF silencing directly to KRAS may ensure that the locus is not reactivated in CRC tumor cells." (PMID 24623306, 2014). "Although KRAS G12-mutated CRCs are generally associated with poor prognosis, a considerable percentage of KRAS WT CRCs showed low DFS and some KRAS G12 mutated CRCs showed high DFS regardless of their tumor stage." (PMID 25090459, 2014). "It has been reported that BRAF and KRAS mutations do not occur concomitantly within the same tumor, as simultaneous mutation in the same RAS/RAF/MEK/ERK signal pathway are redundant for the tumor cells." (PMID 25013473, 2014). "Specifically we expressed different G12V-activated KRAS effector domain mutants (KRASV12, KRASV12/S35, KRASV12/G37, KRASV12/E38 or KRASV12/C40) alone or in conjunction with induction of BrafV600E expression in BrafCA mice and assessed tumor formation and pathology." (PMID 24489653, 2014).